MAGED1 (MAGE family member D1)
Description:
Involved in the apoptotic response after nerve growth factor (NGF) binding in neuronal cells. Inhibits cell cycle progression, and facilitates NGFR-mediated apoptosis. May act as a regulator of the function of DLX family members. May enhance ubiquitin ligase activity of RING-type zinc finger-containing E3 ubiquitin-protein ligases. Proposed to act through recruitment and/or stabilization of the Ubl-conjugating enzyme (E2) at the E3:substrate complex. Plays a role in the circadian rhythm regulation. May act as RORA co-regulator, modulating the expression of core clock genes such as BMAL1 and NFIL3, induced, or NR1D1, repressed.
Synonyms: NRAGE; DLXIN-1
Tractability: Antibody: UniProt places it where antibodies can reach, with medium confidence; its Gene Ontology location is reachable by antibodies, with medium confidence. PROTAC: ubiquitination databases record sites on it.
Gene: Protein-coding gene on chromosome X (51,803,007 to 51,902,357, forward strand). Ensembl gene ENSG00000179222.
Subcellular location: Cytoplasm; Cell membrane; Nucleus
Subcellular location (Human Protein Atlas): Cytosol
Pathways (Reactome):
Gene expression (Transcription): NPAS4 regulates expression of target genes
Programmed Cell Death: Caspase activation via Dependence Receptors in the absence of ligand
Signal Transduction: NRAGE signals death through JNK
Gene Ontology:
Molecular function: identical protein binding; protein binding; transcription coactivator activity
Biological process: negative regulation of epithelial cell proliferation; circadian regulation of gene expression; negative regulation of transcription by RNA polymerase II; regulation of apoptotic process; regulation of DNA-templated transcription; negative regulation of DNA-templated transcription; positive regulation of branching involved in ureteric bud morphogenesis; positive regulation of DNA-templated transcription; regulation of circadian rhythm
Cellular component: protein-containing complex; chromatin; cytosol; nucleus; cytoplasm; plasma membrane
Homologues: Orthologues: chimpanzee MAGED1 (99% identical), macaque MAGED1 (99% identical), rabbit MAGED1 (95% identical), dog MAGED1 (94% identical), pig MAGED1 (94% identical), rat Maged1 (88% identical), mouse Maged1 (88% identical), zebrafish ndnl2 (12% identical), Drosophila melanogaster MAGE (7% identical). Paralogues in human: MAGED4 (41% identical), MAGED4B (41% identical), TRO (34% identical), MAGED2 (33% identical), MAGEL2 (20% identical), MAGEE1 (18% identical), MAGEF1 (15% identical), MAGEB17 (15% identical), MAGEB1 (15% identical), MAGEB6B (15% identical), MAGEB18 (15% identical), MAGEB3 (15% identical), and 25 more.